TGM2 (transglutaminase 2)
Diseases named in the same sentence as TGM2 in open-access papers (continued):
Sharing a sentence is not in itself a finding about the gene and the disease.
cancer (continued). "More interestingly, TGM2 could active PI3K/mTORC1 signaling pathway to be implicated in various aspects of cancer progression including cell survival and chemo-resistance." (PMID 26872016, 2016). "Interestingly, TGM2 is linked to several cancers and the process of epithelial-mesenchymal transition (EMT)." (PMID 23516655, 2013). "Elevated TGM2 levels were associated with an immunosuppressive microenvironment: decreased Th1 (R = -0.186, P < 0.0001) and NK cell infiltration (R = -0.116, P = 0.0092), and increased M2 macrophage (R = 0.164–0.528, P < 0.0001) and cancer-associated fibroblast infiltration (R = 0.469, P < 0.0001)." (PMID 41050683, 2025). "In addition, TGM2 has been implicated in chemoresistance in a variety of cancers." (PMID 41469519, 2025). "As the overexpression of TGM2 in cancer cells is usually linked to transcription level changes of cancer-related genes, TGM2-mediated histone monoaminylation may serve as a key upstream regulation mechanism to manipulate gene transcription in an epigenetic fashion." (PMID 39115570, 2024). "Due to its diverse enzymatic activities, TGM2 has been implicated in many biological processes such as inflammation, wound healing, cell survival, and apoptosis, as well as in the pathophysiology of various diseases such as celiac disease, neurodegenerative disorders, and cancer." (PMID 34103685, 2021). "Secreted CLIC3 regulates the binding of transglutaminase-2 (TGM2) to its cofactors, leading to promotion of angiogenesis and cancer progression by promoting TGM2-dependent invasion." (PMID 41341490, 2025). "Specifically, we found a positive correlation between cancer cell PS exposure and the quantity of secreted M2 markers, such as arginase 1 and TGM2." (PMID 40227806, 2025). "Transglutaminase 2 has emerged as a new and essential survival factor in a variety of cancer cell types." (PMID 41184249, 2025). "This in turn served to drive angiogenesis and cancer progression by promoting TGM2-dependent invasion." (PMID 41008519, 2025). "TGM2, a multifunctional GTPase overexpressed in various human cancers, is an oncogene that has also been reported to contribute to metastasis and drug resistance." (PMID 41463161, 2025). "Through a transglutaminase-2-dependent mechanism, IL-1β increases the aggressiveness of cancer cells in the tumor microenvironment by inducing the production of IL-6." (PMID 40699769, 2025). "Specifically, TGM2 has significant impacts on doxorubicin resistance in cancer treatment and mediates the resistance to neratinib in metastatic breast cancer by up-regulating IL-6 and activating the NF-κB signaling pathways." (PMID 39115570, 2024). "A better understanding of the biochemical and genetic basis of TGM2-mediated histone monoaminylation will facilitate the development of new anti-cancer strategies in the future." (PMID 39115570, 2024). "The two major isoforms of TGM2, TGM2-long and the truncated TGM2-short, are proposed to have opposing roles in cancer, being pro-cell-survival and pro-apoptotic, respectively." (PMID 39516660, 2024). "For example, elevation of TGM2 has been found to account for the resistance to multiple cancer therapies, while down-regulation of TGM2 alleviates chemoresistance and enhances the therapeutic effects." (PMID 39115570, 2024). "Even though the correlation between TGM2 and cancer is clear, the detailed regulatory mechanisms are still poorly understood." (PMID 39115570, 2024). "While there are several reversible and irreversible inhibitors of TGM2, they have only been tested as therapeutic options for the treatment of various cancers." (PMID 39769187, 2024). "In this review, we will mainly focus on the role of TGM2 in cancer, specifically regarding its emerging regulatory function in histone monoaminylation and epigenetics." (PMID 39115570, 2024).
cancer (continued). "In general, the overexpression of TGM2 is linked to the up-regulation of several stemness markers, including CD133, SOX2, and β-catenin, thereby motivating cancer stem cell self-renewal pathways." (PMID 39115570, 2024). "We also included DCN and TGM2 because both are suggested to inhibit metastasis in different cancers by promoting cell–matrix interactions." (PMID 38598843, 2024). "Transglutaminase 2 (TGM2) has been known as a well-characterized factor regulating the progression of multiple types of cancer, due to its multifunctional activities and the ubiquitous signaling pathways it is involved in." (PMID 39115570, 2024). "TGM2 interacts with multiple factors in the KRAS pathway and is associated with the aggregation of KRAS mutant-induced cancer development." (PMID 39115570, 2024). "Previous studies have shown that TGM2 overexpression can promote cancer cell growth via several cell proliferation pathways and the inhibition of apoptosis." (PMID 39115570, 2024). "In these cancer cells, up-regulation of TGM2 protein expression is positively correlated with the development of tumor metastasis phenotypes." (PMID 37115802, 2023). "Atypically expressed transglutaminase 2 (TG2) has been identified as a poor prognostic factor in a variety of cancers." (PMID 36977701, 2023). "TGM2 provides phenotypic advantages to cancer cells by cross-linking ECM proteins such as fibronectin, laminin, and collagen." (PMID 37115802, 2023). "Transglutaminase 2 (TG−2), on the other hand, plays a critical role in shifting glucose metabolism, enabling cancer cells to survive in stressful conditions and enhancing their metastatic potential." (PMID 37049499, 2023). "Transglutaminase 2 (TG2) is a critical cancer cell survival factor that activates several signalling pathways to foster drug resistance, cancer stem cell survival, metastasis, inflammation, epithelial-mesenchymal transition, and angiogenesis." (PMID 37446117, 2023). "TGM2 induces chemoresistance in cancer cells by modulating extracellular matrix structure, inducing EMT, activating survival pathways, especially Wnt/β-catenin signaling, and inhibiting apoptosis and autophagy." (PMID 37535601, 2023). "These new reports provide new glimpses into the role of TGM2 in cancer, although the substantiation of such a claim has been difficult with the scant amount of direct evidence to date." (PMID 36831672, 2023). "In more recent studies, TGM2 was found to inhibit the proliferation, migration, and invasion of cancer cells." (PMID 37115802, 2023). "Several reports have demonstrated elevated expression of TGM2 in various cancer entities, and a correlation of strong TGM2 expression and poor prognosis has been shown." (PMID 37443286, 2023). "TGM2 expression can enable cancer cells to acquire the characteristics of stem cells, thus contributing to self-renewal and survival." (PMID 37115802, 2023). "TGM2 has been shown to be overexpressed in a number of cancer types and is known to play tumor-promoting roles, such as induction of proliferation, invasion, and angiogenesis." (PMID 35867798, 2022). "Inactivation of NF-KB via downregulation of Transglutaminase 2 (TGase2), a cross linking enzyme, leads to apoptosis of drug resistant cancer cells." (PMID 36531159, 2022). "To confirm our findings, we checked the protein expressions of two of these genes—STOM and TGM2 in HeLa WT and KO cells due to their reported roles in promoting metastasis in different cancer entities." (PMID 36399280, 2022). "Here, we identify a novel aspect of the metastatic cascade by which weakly migratory cancer cells release tissue transglutaminase 2 (Tg2)-rich MVs to activate fibroblasts and enhance cancer cell dissemination." (PMID 36475545, 2022).
cancer (continued). "TGM2 confers a strong protective role on cancer cells against apoptotic stresses and thereby promotes cancer cells survival." (PMID 35853996, 2022). "Weakly migratory cells release microvesicles rich in tissue transglutaminase 2 (Tg2) which activate murine fibroblasts and lead weakly migratory cancer cell migration in vitro." (PMID 36475545, 2022). "The accelerated TGM2 expression and activity in cancer tissue prompted us to investigate the functional significance of TGM2 upregulation in CRC." (PMID 34103685, 2021). "DNAJA1/HDJ2 also binds to an enzyme involved in extracellular matrix cross-linking and remodeling, transglutaminase 2 (TG2) that is associated with cell survival and cancer progression." (PMID 34948322, 2021). "These seemingly contradictory cellular functions attributed to TGM2 are puzzling and demonstrate the importance to consider the different enzymatic activities as well as isoforms of TGM2 in studies of its role in cancer biology." (PMID 34103685, 2021). "For these reasons, our study aims to define the role of the recently characterized TG2-lncRNA, located within the first intron of TGM2 gene, which is well-known to be involved in the development of various types of cancer." (PMID 34449674, 2021). "The role of TGM2 in cancer has been controversial, and a tumor suppressive function, as well as an oncogenic role, have been reported." (PMID 34103685, 2021). "In this regard, we recently discovered a polyadenylated long non-coding RNA (named TG2-lncRNA) encoded within the first intron of the Transglutaminase type 2 gene (TGM2), which is related to tumour proliferation in human cancer cell lines." (PMID 34449674, 2021). "TGM2 promoter contains response elements to inflammation and hypoxia, which are greatly elevated in the environment surrounding malignant tumors, leading to an increased expression of TG2." (PMID 34360011, 2021). "TGM2 functions in many biological processes, such as extracellular matrix stabilization, cell differentiation, maintenance of cancer stem cell survival, and invasive and metastatic behavior." (PMID 33738254, 2021). "TGM2 was the first TG member to be discovered and is a multifunctional protein involved in the pathogenesis of multiple types of cancers." (PMID 33845796, 2021). "In various cancer entities, an implication of TGM2 in cancer development, progression, metastasis, and cancer stem cell maintenance has long been discussed." (PMID 34103685, 2021). "Our study provides additional mechanisms involving TGM2 in cancer aggressiveness through enhancing tumor-promoting inflammation." (PMID 32467608, 2020). "The network surrounding Il10ra shows that many of them are cancer related, e.g., Reg3g, Aoc1, Mep1a, Irf7, Gas6, B3gnt7, Tap1, Tgm2, and Nos2." (PMID 33396408, 2020). "This study highlights the role of transglutaminase 2 in selective mRNA translation of hypoxic cancer cells by polyamination-dependent modulation of 4EBPs, providing a target for cancer treatment." (PMID 32075852, 2020). "Transglutaminase 2 (TG2) - the multifunctional transamidase is a YAP/TAZ target gene that is important for cancer stem cell survival and for maintaining integrin expression." (PMID 32206112, 2020). "Then, we compared the expression of TGM2 and LAMP2b, previously proven as a marker of acidosis in solid tumors in human cancers, in each patient." (PMID 33294017, 2020). "Overexpression of TGM2 has been reported in many cancer types, and high expression levels of TGM2 are highly correlated with metastasis, drug resistance and a poor survival rate in cancer patients." (PMID 32467608, 2020). "The expression of the enzyme transglutaminase 2 (TGM2) has been shown to increase in several types of cancer, but its precise role has been unclear." (PMID 32467608, 2020).
cancer (continued). "In GC, TGM2 was reported to promote the proliferation, migration and invasion of cancer cells by activating the ERK 1/2 pathway." (PMID 32467608, 2020). "Several lines of evidence suggest that a key role in inflammatory processes and in the inflammation-induced progression of several types of cancers is played by transglutaminase 2 (TG2) or tissue transglutaminase." (PMID 31360119, 2019). "TGM2, a membrane enzyme involved in protein cross-linking and cell adhesion to fibronectin, has been reported to be related to cancer stem cell survival and tumor formation in multiple types of cancers." (PMID 31570702, 2019). "In the case of TGM2, it not only was predicted to be downregulated as an upstream regulator but also showed decreased mRNA levels, which is consistent with data from cancer patients." (PMID 30918060, 2019). "The observation that hepatic stellate cells induce upregulation of TGM2, producing high basal expression of HIF-1α, is of immense importance, suggesting a major role for TGM2 in inflammation-regulated cancer progression." (PMID 30393774, 2018). "This work reveals a previously undescribed invasive mechanism whereby the secretion of a glutathione-dependent oxidoreductase drives angiogenesis and cancer progression by promoting TGM2-dependent invasion." (PMID 28198360, 2017). "Next, we assessed the requirement of TGM2 in extracellular CLIC3 ability to promote cancer cell invasion." (PMID 28198360, 2017). "Taken together, these data indicate that secreted CLIC3 requires the activity of extracellular TGM2 and α5β1 integrin to promote the invasive behaviour of both ECs and cancer cells." (PMID 28198360, 2017). "Secreted CLIC3 promotes invasive behaviour of endothelial cells to drive angiogenesis and increases invasiveness of cancer cells both in vivo and in 3D cell culture models, and this requires active transglutaminase-2 (TGM2)." (PMID 28198360, 2017). "Here we have identified a new pathway whereby extracellular CLIC3 cooperates with TGM2 to drive endothelial and cancer cell invasion." (PMID 28198360, 2017). "The ability of rCLIC3 to drive pseudopod elongation was completely ablated when cancer cells were plated into ECM generated by TGM2 knockdown fibroblasts." (PMID 28198360, 2017). "To evaluate the clinical relevance of Gαh overexpression (OE), we performed a global prognostic meta-analysis for the Gαh gene (TGM2) on microarray data from clinical cohorts with different cancer types using PrognoScan." (PMID 28576130, 2017). "TGM2 was also reported to be upregulated in cancer cell lines by several important signaling pathways involved in tumor progression or metastasis, such as NFKB1/NF-κB, TGFB1/TGF-beta, RARA/RAR-alpha, and upon genotoxic stress." (PMID 26956429, 2016). "TGM2-triggered pro-survival events including NF-κB activation will lead us to an understanding of rapamycin resistance in mTORC1-hyperactive cancer cells." (PMID 26872016, 2016). "Here, we report that inhibition of transglutaminase 2 (TGM2), a compensatory response to rapamycin treatment, potently sensitizes mTORC1-hyperactive cancer cells to rapamycin treatment." (PMID 26872016, 2016). "TGM2 inhibition potently sensitizes mTORC1-hyperactive cancer cells to rapamycin treatment, and a rapamycin-induced autophagy blockade inhibits the compensatory TGM2 upregulation." (PMID 26872016, 2016). "More interestingly, TGM2 blockade sensitizes mTORC1-hyperactive cancer cells to rapamycin treatment." (PMID 26872016, 2016). "Our data suggest that TGM2 upregulation is a common mechanism for rapamycin-triggered events in mTORC1-hyperactive cancer cells." (PMID 26872016, 2016). "Further study downstream of TGM2 in rapamycin-resistant cancer cells is urgently needed to establish an understanding of the cytostatic mechanism of rapamycin." (PMID 26872016, 2016).
cancer (continued). "Overexpression of Transglutaminase 2 (TG2), a multifunctional enzyme, in cancer cells impacts epithelial mesenchymal transition, growth, invasion and interactions with tumor microenvironment." (PMID 24058567, 2013). "All the down-regulated genes, in this Panel 3 showed their significant up-regulation in most of many types of cancers (TGM2, CSNK1A1, CTNNA1, NAMPT/Visfatin, TNFRSF1A, ETS1, SRC-1, FN1, APLP2, DMBT1/SAG, AIB1, AZIN1)." (PMID 23122428, 2012). "Transglutaminase 2 (TG2) and its phosphorylation have been consistently found to be upregulated in a number of cancer cell types." (PMID 22759359, 2012). "The expression of proinflammatory protein tissue transglutaminase 2 (TG2) is frequently upregulated in multiple cancer cell types." (PMID 22225906, 2012). "Though this evidence strongly suggests a role for TGM2 in cancer, the exact molecular mechanism which by high levels of TGM2 expression lead to an adverse prognosis in laryngeal SCC is not know and requires further research." (PMID 22458929, 2012). "Expression of transglutaminase 2 (TGase 2) is related to invasion and resistance to chemotherapeutic agents in several cancer cells." (PMID 21943122, 2011). "Previous studies have identified TGM2 as a potential therapeutic target in cancer treatment." (PMID 41009970, 2025). "Moreover, the formation of a CD44v6/transglutaminase 2 (TG2)/ERK1/2 protein complex was shown to promote cancer cell growth and resistance to apoptosis." (PMID 40114966, 2025). "Building off our previous work with TGM2, our lab reported the use of bioorthogonal probes to study the regulatory function of histone monoaminylation (i.e. serotonylation and dopaminylation) in cancer cell chromatin." (PMID 41001731, 2025). "Additionally, TGM2-dependent covalent CXCL12-Keratine 19 heterodimers can coat cancer cell surfaces, potentially interfering with T-cell-mediated immune responses, suggesting a role for CK-19 in immune regulation." (PMID 38813379, 2024). "Finally, we will summarize the key technical approaches for a better understanding of TGM2-mediated histone monoaminylation and its role in cancer biology." (PMID 39115570, 2024). "As serotonin, dopamine, and histamine are all important signaling metabolites that are enriched in tumor microenvironment, TGM2-mediated histone monoaminylation is supposed to serve as a biomarker accumulated in cancer cells and extensively regulate cancer-related genes in an epigenetic manner." (PMID 39115570, 2024). "Therefore, TGM2 represents not only a biomarker for cancer prognosis, but also a therapeutic target with significant clinical implications." (PMID 39115570, 2024). "Recent discoveries revealed histone as an important category of TGM2 substrates, thus identifying histone monoaminylation as an emerging epigenetic mark, which is highly enriched in cancer cells and possesses significant regulatory functions of gene transcription." (PMID 39115570, 2024). "Previous research has also shown that TGM2 is closely related to cancer treatment efficacy." (PMID 39115570, 2024). "However, more recent inhibitors have been discovered through various means, which not only reduced TGM-2 but also other factors such as MMP9, TIMP1 and 2; TNF-α and β, which increases cancer cells’ susceptibility to chemotherapy and inflammation." (PMID 37509081, 2023). "The inhibition of TGM2 suppressed CRC proliferation and tumor growth in vivo, suggesting that TGM2 may be a novel target in patients with strong TGM2 expression for clinical cancer therapy." (PMID 37443286, 2023). "TGM2 is overexpressed in many types of cancer, promoting proliferation, migration, and invasion." (PMID 38283944, 2023). "Importantly, TGM2 is overexpressed in various kinds of cancers, making it a promising target for cancer therapies." (PMID 37735413, 2023).